JPH3 (junctophilin 3)
Description:
Junctophilins contribute to the formation of junctional membrane complexes (JMCs) which link the plasma membrane with the endoplasmic or sarcoplasmic reticulum in excitable cells. Provides a structural foundation for functional cross-talk between the cell surface and intracellular calcium release channels. JPH3 is brain-specific and appears to have an active role in certain neurons involved in motor coordination and memory.
Synonyms: JP-3; JP3; TNRC22; CAGL237; HDL2
Tractability: Antibody: UniProt places it where antibodies can reach, with medium confidence; UniProt predicts a signal peptide or a membrane-spanning region; its Gene Ontology location is reachable by antibodies, with medium confidence. PROTAC: its protein half-life has been measured.
Gene: Protein-coding gene on chromosome 16 (87,601,835 to 87,698,156, forward strand). Ensembl gene ENSG00000154118.
Subcellular location: Cell membrane; Endoplasmic reticulum membrane
Subcellular location (Human Protein Atlas): Nucleoplasm; Cytosol
Gene Ontology:
Molecular function: protein binding
Biological process: calcium ion transport into cytosol; regulation of cardiac muscle contraction by calcium ion signaling; regulation of release of sequestered calcium ion into cytosol by sarcoplasmic reticulum; regulation of synaptic plasticity; exploration behavior; memory; regulation of neuronal synaptic plasticity
Cellular component: endoplasmic reticulum membrane; junctional membrane complex; junctional sarcoplasmic reticulum membrane; membrane; plasma membrane; endoplasmic reticulum
Genetic constraint (gnomAD): Loss-of-function variants: 11 observed, 50.64 expected, observed/expected ratio (o/e) 0.22, 90% interval 0.14 to 0.36. The synonymous counts are far from expectation, so gnomAD's model fits this gene poorly and the ratio says little. Missense variants: 1,201 observed, 1,052.1 expected, observed/expected ratio (o/e) 1.14, 90% interval 1.09 to 1.2. Synonymous variants: 673 observed, 463.54 expected, observed/expected ratio (o/e) 1.45, 90% interval 1.36 to 1.55.
Homologues: Orthologues: chimpanzee JPH3 (99% identical), macaque JPH3 (98% identical), rat Jph3 (92% identical), dog JPH3 (91% identical), mouse Jph3 (91% identical), guinea pig JPH3 (89% identical), tropical clawed frog jph3 (80% identical), zebrafish jph3b (71% identical), Caenorhabditis elegans jph-1 (37% identical), Drosophila melanogaster jp (32% identical). Paralogues in human: JPH1 (47% identical), JPH2 (45% identical), JPH4 (37% identical).
Diseases named in the same sentence as JPH3 in open-access papers:
JPH3 is named in the same sentence as 66 diseases in open-access papers, as found by Europe PMC text mining. Sharing a sentence is not in itself a finding about the gene and the disease. The quoted sentences say what the papers report.
Huntington disease-like 2 (13 papers, 2009 to 2025). Huntington disease-like 2 (HDL2) is a severe neurodegenerative disorder considered part of the neuroacanthocytosis syndromes characterized by a triad of movement, psychiatric, and cognitive abnormalities. "Inherited defects in JPH3 were the first junctophilin gene disorder associated with a human disease, namely Huntington Disease-Like 2 (HDL2)." (PMID 35001666, 2022). "Jph3 hemizygous and null knockout mice exhibiting abnormal motor function were recently compared with Huntington disease-like 2 and Huntington disease mouse models, extending mechanisms both through a multifactorial toxic gain-of-function of Jph3 RNA and a loss of JPH3 expression." (PMID 35001666, 2022). "These genes are PANK2, which encodes a mitochondrial protein whose mutations results in Panthothenate Kinase-Associated Neurodegeneration (PKAN), and JPH3, which encodes junctophilin 3, an ER-to-PM tether whose mutations result in the so-called Huntington Disease Like 2 (HDL2)." (PMID 35994651, 2022). "Trinucleotide repeat expansions in the JPH3 gene cause a neurodegenerative disease known as Huntington Disease-Like 2 (HDL-2)." (PMID 35001666, 2022). "Huntington’s disease-like 2 (HDL2) affects patients of African ancestry and is caused by CTG/CAG repeat expansions in the Junctophilin-3 gene (JPH3)." (PMID 30291526, 2018). "Shortly after the discovery of junctophilins, a CAG/CTG repeat expansion in an alternatively spliced exon of JPH3 was found to cause Huntington disease-like 2 (HDL2), a disease clinically indistinguishable from Huntington’s disease." (PMID 34305529, 2021). "Dominant mutations in the JPH3 gene caused by an expanded CAG/CTG repeat in its alternatively spliced exon 2A are responsible for Huntington's disease-like 2 (HDL2), a phenocopy clinically indistinguishable from Huntington's disease (HD)." (PMID 29208631, 2018).
Huntington disease (8 papers, 2015 to 2025). Huntington disease (HD) is a rare neurodegenerative disorder of the central nervous system characterized by unwanted choreatic movements, behavioral and psychiatric disturbances and dementia. "Jph3 mutations are linked to neuropathological conditions in the brain, such as Huntington’s disease." (PMID 26271746, 2015). "A monoallelic trinucleotide repeat expansion located within the junctophilin-3 gene (JPH3) has been implicated in a rare autosomal dominant (AD) late-onset (and progressive) disorder clinically resembling Huntington disease (HD), and known as HD-like 2 (HDL2; MIM# 606438)." (PMID 33824468, 2021). "Of Black South African patients with symptoms of Huntington Disease who tested negative for Huntington (HTT) gene expansions, ∼35% will have expansions of the JPH3 gene consistent with HDL2." (PMID 35001666, 2022).
Chorea (3 papers, 2020 to 2024). Chorea (Greek for 'dance') refers to widespread arrhythmic involuntary movements of a forcible, jerky and restless fashion. "As far as HD and HD phenocopies are concerned, we suggest to take into account the research for JPH3 expansion in a patient with chorea and likely African ancestry whose HD test is negative." (PMID 36237940, 2022).
gastric cancer (3 papers, 2021 to 2023). A primary or metastatic malignant neoplasm involving the stomach. "Previously, JPH3 was identified as a novel methylated tumor-suppressor gene, which was shown to be a tumor suppressor gene in colorectal and gastric cancers." (PMID 37670265, 2023).
lung carcinoma (2 papers, 2017 to 2018). "These genes include ICAM5, JPH3, MGMT, MMP2, RASSF1α etc. that are frequently silenced by epigenetic mechanisms in lung cancers." (PMID 30348169, 2018).
Abdominal obesity (1 paper, 2019). Excessive fat around the stomach and abdomen. "The top four CpGs that were found to be differentially methylated between individuals with and without abdominal obesity were located at the genes c13orf36, ZC3H12D, MYO9B, and KCNG3 in females; and JPH3, TCP11L1, and GRIK3 in males (one CpG had no annotated gene)." (PMID 31212707, 2019).
autism spectrum disorder (1 paper, 2021). A spectrum of developmental disorders that includes autism, and Asperger syndrome. "Furthermore, a recent genome-wide analysis established a significant association between a single nucleotide polymorphism in JPH3 (rs1864152) and higher risks of autism spectrum disorders." (PMID 33824468, 2021).
chorea-acanthocytosis (1 paper, 2013). Chorea-acanthocytosis (ChAc) is a form of neuroacanthocytosis and is characterized clinically by a Huntington disease-like phenotype with progressive neurological symptoms including movement disorders, psychiatric manifestations and cognitive disturbances. "Chorea-acanthocytosis (ChAc) relates to mutations in VPS13A, McLeod Syndrome (MLS) has mutations in XK, Huntington’s Disease-like 2 (HDL2) in JPH3, and panthotenate kinase-associated neurodegeneration (PKAN) in PANK2." (PMID 24098554, 2013).
colorectal cancer (1 paper, 2021). A primary or metastatic malignant neoplasm that affects the colon or rectum. "JPH3 is recognized as the new tumor suppressor gene with methylation within colorectal cancer, thus enhancing apoptosis mediated by mitochondria." (PMID 35222516, 2021).
dilated cardiomyopathies (1 paper, 2018). "Moreover, mutations in the human JPH2 gene are associated with hypertrophic and dilated cardiomyopathies; mutations in JPH3 are responsible for the neurodegenerative Huntington's disease-like-2 (HDL2), whereas JPH1 acts as a genetic modifier in Charcot–Marie–Tooth 2K peripheral neuropathy." (PMID 29208631, 2018).
epilepsy (1 paper, 2024). A brain disorder characterized by episodes of abnormally increased neuronal discharge resulting in transient episodes of sensory or motor neurological dysfunction, or psychic dysfunction. "Ultimately, 5 target genes were obtained, of which P2RX7 and TMTC2 were upregulated and CACNA1C, JPH3 and GRM1 were downregulated in epilepsy." (PMID 38191407, 2024).
glioma (1 paper, 2020). A benign or malignant brain and spinal cord tumor that arises from glial cells (astrocytes, oligodendrocytes, ependymal cells). "Most of them were reported in glioma, CACNG2 JPH3, TUBB6, NRSN1, FAM19A2, NALCN, GNAL have not been reported yet." (PMID 32406502, 2020). "CACNG2, JPH3, TUBB6, NRSN1, FAM19A2, NALCN, GNAL have not been reported in gliomas." (PMID 32406502, 2020). "In addition, there is no report about CACNG2, JPH3, TUBB6 (tubulin β 6 class V), NRSN1, FAM19A2, NALCN, CDH18, GNAL on glioma." (PMID 32406502, 2020). "In addition, CACNG2, JPH3, TUBB6, NRSN1, FAM19A2, NALCN, GNAL were not reported in glioma." (PMID 32406502, 2020).
Infertility (1 paper, 2025). "These latter SNPs are located in two genes, Zinc Finger CCHC-Type Containing 14 (ZCCHC14) and Junctophilin 3 (JPH3), neither of which have any previously published connections to infertility." (PMID 41325449, 2025).
Intellectual disability (1 paper, 2021). "Interestingly, a previous study identified by array-CGH a 16q24.1-16q24.2 deletion in a child affected with intellectual disability and seizures and the identified deletion encompassed in total four genes, of which JPH3 had the highest LoF intolerance scores." (PMID 33824468, 2021).
lung adenocarcinoma (1 paper, 2021). A carcinoma that arises from the lung and is characterized by the presence of malignant glandular epithelial cells.
Sepsis (1 paper, 2019). Sepsis is defined as life-threatening organ dysfunction caused by a dysregulated host response to infection. "Previous research has described an increased expression of synaptic genes during the progression from normal aging to neurodegenerative disease, including genes we observed to increase in older males on day 4 of sepsis (Cacnb1, Cacna1a, Ephb4, Glul, Jph3, Mink1, Nrxn2, Grasp)." (PMID 31278440, 2019).
type 2 diabetes (1 paper, 2016). "Furthermore, acute knockdown of Mfn2 directly leads to impaired GSIS in islet, which highlights the possibility that decrease in Mfn2 expression due to JPH3 downregulation in beta cells might cause development of type 2 diabetes." (PMID 27336719, 2016). "Our findings suggest that decrease of JPH3 is responsible for impaired GSIS, and also imply a causal link between JPH3 defects and type 2 diabetes." (PMID 27336719, 2016).
neurological disorders (2 papers, 2021 to 2025). "We also discuss the heterogeneous clinical phenotypes and molecular mechanisms implicated in JPH3-related neurological disorders." (PMID 33824468, 2021). "Additionally, neurological disorders linked to mutations within the synprint region of CaV2.1 might partly arise from altered interactions with JPH3." (PMID 40118452, 2025). "Based on the results identified in this study, we suggest that JPH3 is a dosage-sensitive (haploinsufficient) disease gene and some allelic and phenotypic heterogeneity may occur in JPH3-related neurological disorders." (PMID 33824468, 2021).
infection (1 paper, 2022). The state of being infected such as from the introduction of a foreign agent such as serum, vaccine, antigenic substance or organism. "Four weeks post infection, several muscle-related mouse proteins to were up-regulated, such as actin-related protein 5, junctophilin-3, ATP-sensitive inward rectifier potassium channel 11 and tissue-nonspecific alkaline phosphatase." (PMID 35271623, 2022).
movement disorder (1 paper, 2021). Neurological conditions resulting in abnormal voluntary or involuntary movement, which may impact the speed, fluency, quality and ease of movement. "Our study implicates a disruptive JPH3 LoF variant in heterogeneous neurodevelopmental issues and movement disorders with onset in the infantile age." (PMID 33824468, 2021).
neurogenetic diseases (1 paper, 2020). "Several neurogenetic diseases are manifested with the HD phenotype, such as “HDL1” (caused by an 8-octapeptide insertion in the PRNP gene), “HDL2” (caused by mutations in JPH3) and “HDL4” (SCA17)." (PMID 32775019, 2020).
JPH3 also shares sentences with these, for which no sentence is quoted: myotonic dystrophy type 1 (4 papers); spinocerebellar ataxia (4); tumor (4); amyotrophic lateral sclerosis (3); Dystonia (3); aceruloplasminemia (2); breast carcinoma (2); cancer (2); dentatorubral-pallidoluysian atrophy (2); Friedreich ataxia (2); frontotemporal dementia (2); neurodegenerative disease (2); Obesity (2); abetalipoproteinemia (1); Acanthocytosis (1); acute coronary syndrome (1); acute myocardial infarction (1); anaplastic thyroid cancer (1); Ataxia (1); atherosclerosis (1); autoimmune disease (1); benign hereditary chorea (1); brain disorder (1); Cognitive impairment (1); colon cancers (1); colon tumors (1); COVID-19 (1); dementia (1); developmental delay (1); fragile X-associated tremor/ataxia syndrome (1).
A further 15 diseases each share a sentence with JPH3 in 1 paper.